IL1B (interleukin 1 beta)
Diseases named in the same sentence as IL1B in open-access papers (continued):
Sharing a sentence is not in itself a finding about the gene and the disease.
Obesity (continued). "A significant depletion of this species has been observed in tumor-bearing mice in an experimental model of colon cancer, obesity-driven in genetically deficient mice (Apc1638N) and its abundance was inversely correlated with colonic interleukin IL-1β levels." (PMID 32947881, 2020). "Adipocytes in obesity secreted high IL‐1β, recruiting tumour‐associated neutrophils (TAN) which induces activation of pancreatic stellate cells (PSC)." (PMID 32458441, 2020). "TLR expression exhibits circadian dynamics that are dependent, in part, on gut microbes and their activation can result in downstream induction of pro-inflammatory cytokines, including TNF-α, IL-6, and IL-1β, driving obesity-associated inflammation." (PMID 33255707, 2020). "When mice were fed a high fat diet, they showed signs of systemic inflammation (C5a, IL-6, CCL2, IL-1β), consistent with the notion that obesity is a risk factor to develop “a state of chronic low-level inflammation”." (PMID 32971872, 2020). "Inflammation plays a fundamental role in the pathophysiology of obesity, and pro-inflammatory cytokines IL-1β and IL-18 have already been linked to this metabolic disorder." (PMID 31998283, 2019). "Especially, upregulation of IL-1β is a general feature underlying obesity-related insulin resistance, which increases intestinal epithelial tight junction permeability and inflammation." (PMID 31551944, 2019). "Obesity is associated with increased expression of proinflammatory cytokines such as IL-6, TNFα, and IL-1β in adipose tissue." (PMID 31828157, 2019). "Obesity results in elevation of inflammatory cytokines such as interleukin-6 (IL-6), tumor necrosis factor-alpha, (TNFα), and interleukin-1 beta (IL-1β), which have all been linked to the development of breast cancer." (PMID 31007849, 2019). "Several lines of evidence implicated IL-1β in the pathogenesis of high-fat diet-induced inflammation together with increased expression in the adipose tissue in human obesity and insulin resistance." (PMID 29643979, 2018). "In obesity-associated breast cancer, adipocytes are able to recruit macrophages by a novel signaling pathway involving IL-1β and the chemotactic factor CCL2 (also known as MCP-1) that in turn activate CXCL12 promoting angiogenesis and tumor development." (PMID 30619282, 2018). "In mouse models, it has been shown that HFDs and obesity can activate hepatic NF-κB which causes hepatic inflammation and increases the levels of IL-6, IL-1β, and TNF-α." (PMID 30026676, 2018). "Despite unequivocal evidences causally link IL-1β to the development of obesity-associated comorbities, IL-18, also activated by caspase-1, has been shown to ameliorate the development of obesity and insulin resistance." (PMID 30619282, 2018). "Recent studies reported that inflammatory cytokines such as leptin, adiponectin, and IL-1β are involved in obesity-associated OA progression." (PMID 29843440, 2018). "Obesity causes lipid accumulation in adipocytes that can increase the production of proinflammatory cytokines such as TNF-α, IL-6, and IL-1β, and this obesity-associated chronic low-grade inflammation leads to insulin resistance." (PMID 29082259, 2017). "Inflammation of adipose tissue in obesity is associated with increased IL-1β, IL-6 and TNF-α secretion and proposed to contribute to insulin resistance." (PMID 27840174, 2017). "Recent studies showed that innate lymphoid cell 3-induced IL-17 production was related to obesity-associated AHR through macrophage-derived IL-1β and that blockade of TNF-α attenuated ozone-induced neutrophilic inflammation and AHR in obesity." (PMID 28365872, 2017). "The nucleotide-binding domain, leucine-rich-containing family, pyrin domain-containing-3 (abbreviated as NLRP3) inflammasome senses obesity-associated danger signals, leading to caspase-1 activation and subsequent secretion of IL-1β and IL-18." (PMID 27070576, 2016).
Obesity (continued). "Increased plasma levels of both fibrinogen and IL-1β were associated with high risk for overweight and obesity (p < 0.05)." (PMID 25897330, 2015). "Testosterone status and diet-induced obesity were associated with significant regulation of macrophage infiltration, mRNA levels of IL-1β, TNFα, and P0, and activity levels of Na+,K+-ATPase." (PMID 25224590, 2014). "Secreted IL-1β is said to be associated with atherosclerosis, diabetes, obesity, gout and autoimmune disease." (PMID 24671176, 2014). "Not only has leptin been associated with obesity, but it has also been demonstrated to increase levels of cytokines such as IL-6 and IL-1b, cytokines that were also elevated in our study." (PMID 24732966, 2014). "Obesity-related type 2 diabetes is associated with chronic inflammation and IL-1β levels have been shown to be correlated with obesity and obesity related disorders." (PMID 25403235, 2014). "IL-1β has been implicated as a key regulator in the translation of obesity-associated inflammation into insulin resistance in rodent models." (PMID 24918199, 2014). "IL-1β is implicated in the development of diverse pathologies, including obesity, atherosclerosis, diabetes and several pulmonary illnesses such as asthma, pulmonary obstructive chronic disease and ARDS progression through edema accumulation." (PMID 24788150, 2014). "Secreted active IL-1β is said to be associated with atherosclerosis, diabetes, obesity, gout and autoimmune disease." (PMID 24671176, 2014). "Collectively, our findings suggest that IL-1β signaling upregulates hepatic lipogenesis in obesity, and is essential for the induction of pathogenic hepatic steatosis in obese mice." (PMID 25216251, 2014). "The fundamental role of IL-1β in inflammatory cascades is well established, as is now the recognition of adipose tissue inflammation in obesity-associated-morbidities." (PMID 23341960, 2013). "Emerging evidence has demonstrated that saturated fatty acids prime pro-IL-1β production and inflammasome-mediated IL-1β activation is critical in obesity-associated insulin resistance (IR)." (PMID 23921145, 2013). "Obesity-associated inflammatory genes such as IL1B, IL1ra, IL8, and PTGS2 were also increased by AhR ligands in hMADS cells." (PMID 22262711, 2012). "In a previous study, we reported an association between the polymorphism in the IL-1β gene and obesity in women." (PMID 22216303, 2011). "We therefore investigated the associations between IL-1B C-31T genotypes and indices of obesity among a population of adult Japanese." (PMID 19398847, 2009). "The men and women with the TT genotype of IL-1B C-31T had a higher risk for obesity than those with the CC genotype." (PMID 19398847, 2009). "Men and women with the TT genotype of IL-1B C-31T had a higher risk for obesity than those with the CC genotype." (PMID 19398847, 2009). "The present study showed that IL-1B C-31T genotype was associated with obesity among a sample of the Japanese population." (PMID 19398847, 2009). "This is the first report of an association between the IL-1B C-31T polymorphism and obesity among the Japanese population." (PMID 19398847, 2009). "Cardiovascular diseases, diabetes, obesity, cancer and other pathologies are associated with increased production of thromboxane A2, leukotriene B4, Il-1β, IL-6 and TNF." (PMID 17313679, 2007). "Therefore, further studies should focus on studying how obesity-associated CC as well as IL-1β and CCL2 affect the macrophage differentiation directly in the TME." (PMID 39305371, 2025). "IL-1β may also increase the expression of leptin mRNA in adipose tissue, adding to the underlying causes of obesity development." (PMID 38178093, 2024). "IL-1β stimulates insulin secretion through central muscarine signaling, which leads to increased food intake; it also inhibits fat breakdown to cause fat accumulation in the body, resulting in obesity." (PMID 39830328, 2024).
Obesity (continued). "Previously, we and others reported that the increased adipose expression of CXCL10 in individuals with obesity was associated with inflammatory (IL-1β expression, C-reactive protein levels) and other factors (BMI, CXCR3, and reduced neovascularization causing adipose tissue hypoxia)." (PMID 39065674, 2024). "Interestingly, v.ASC reflected the inflammatory status associated with the metabolic disturbances (T2D and obesity) than sc.ASCs did, by expressing higher levels of IL-1β, IL-6, MCP-1, TNF-α, inflammasome components and caspase-1." (PMID 37962697, 2024). "An increased CARD11+ population in LPS-stimulated IL-1β+CD16+ monocytes may be involved in obesity-associated AHR." (PMID 39672814, 2024). "Furthermore, the study suggests an association between the IL-1β/Caspase-1 cytokine cascade and the pathogenesis of early-stage nephropathy in relation to obesity and diabetes." (PMID 37375705, 2023). "Therefore, further studies are needed to confirm the benefits of evaluating salivary IL-1β concentrations in obese adults as risk factors for metabolic disturbances associated with obesity." (PMID 36835557, 2023). "Obesity-associated dysfunctional adipose tissue (AT) also secretes pro-oncogenic factors such as TNFα, IL-6, IL-1β and provides a carcinogenesis-promoting microenvironment for breast cancer development and progression; it is therefore a fundamental factor of postmenopausal breast cancer development." (PMID 36774339, 2023). "As IL-1β is closely associated with obesity and inflammatory fatty liver disease, HFD-induced NAFLD may be a factor in enhancing the risk of biogenic amines." (PMID 36899958, 2023). "Furthermore, IL-1β is under investigation as a key molecule in inflammasome activation in obesity-associated cancers." (PMID 37509120, 2023). "The low-grade systemic inflammation associated with obesity increases periodontal inflammation and promotes bone resorption processes caused by the recruitment of immuno-inflammatory cells and certain cytokines (IL-1β, TNF)." (PMID 37894804, 2023). "The main findings suggest that the KD, as a source of ketone bodies in the blood, improves glutamate activity by reducing obesity, which is associated with insulin resistance and dyslipidemia, promoting central inflammation (particularly through an increase in interleukins IL-1β, IL-6, and IL-17)." (PMID 37693246, 2023). "Obesity renders macrophages more susceptible to [Ca2+]ex-induced IL-1β release and pyroptosis." (PMID 35931812, 2022). "Strikingly, impairment of HSC function has now been reported to occur prior to the onset of obesity-induced accumulation of adipose tissue CD11c+ macrophages and the inflammation associated with the IL-1β- and TNFα-driven myeloid/lymphoid skewing of BM progenitors." (PMID 36105811, 2022). "These proinflammatory markers may be a direct source or a consequence of obesity, particularly IL-1β, IL-6, and TNF-α, which are associated with chronic and acute inflammation related to obesity." (PMID 36304965, 2022). "Since IL-1β levels are associated with obesity in humans and mice and we have previously shown that GLUT6 expression is regulated by NF-κB, it is also possible that GLUT6 expression may be elevated in specific β-cells clusters within islets." (PMID 36077188, 2022). "Some studies have reported also IL1B polymorphisms as related to obesity." (PMID 35139823, 2022). "As IL-1β is increased in the lungs of LPS-exposed mice and has been linked to obesity-associated AHR, we investigated whether IL-1β might be important to induce AHR in this model." (PMID 35371094, 2022). "The NLRP3 inflammasome activates Caspase 1 and causes release of IL-1β, which in turn has been identified as the major driving force behind leukocytosis in obesity due to its stimulatory effect on myeloid stem cells, but also as contributing factor to the development of type 2 diabetes." (PMID 35931812, 2022).
Obesity (continued). "Tumor necrosis factor alpha (TFNα), interleukin 1-beta (il-1β), and il-6 were demonstrated to be adipokine associated with insulin resistance, at inflammation, and fatty liver, and their expression was also increased in human obesity." (PMID 35887189, 2022). "We also assessed whether the expression of the pro-inflammatory cytokine interleukin-1β (IL-1β), a key factor in the inflammation associated with obesity and metabolic syndrome, was modulated in the heart upon HFHS and by NOX1-deficiency." (PMID 34849611, 2022). "Interestingly, clinical and experimental studies have reported elevated levels of inflammatory cytokines—(interleukin-6 (IL-6), interleukin-1beta (IL-1b), tumor necrosis factor alpha (TNFa)—associated with obesity or HFD consumption." (PMID 34067897, 2021). "Since IL1β strongly correlates with BMI, insulin resistance, and chronic inflammation and is implicated in various cardiometabolic conditions, such as obesity, diabetes, and atherosclerosis, these factors should be taken into consideration when proinflammatory cytokines are studied." (PMID 35002816, 2021). "Furthermore, calorie restriction, exercise and weight loss through bariatric surgery have been associated with lower gene expression of NLRP3 and IL-1β, thus suggesting that obesity-induced MetS and NLRP3 inflammasome activity are interrelated." (PMID 34362072, 2021). "IL-1 family, including IL-1α and IL-1β, is considered the most key cytokine associated with the pathogenesis of OA that induces the inflammatory catabolic process combined with other catabolic factors such as aging, obesity, and traumatic joint injury." (PMID 33833854, 2021). "Different genotypes of rs1143627 (in IL1B) have distinct phenotype correlations; A/G heterozygotes among elderly Swedish men have less total fat and a lower BMI, whereas AA genotype carriers in Japan are at a higher risk of obesity." (PMID 34834553, 2021). "Lower levels of plasma IL-10 after bariatric surgery, alongside its close association with IL-1β, suggest that IL-10 might be secreted in obesity as a compensatory anti-inflammatory mechanism." (PMID 34108550, 2021). "Obesity is strongly associated with chronic inflammatory processes and when examining inflammation-related genes such as IL-1β as well as TNF-α we found a significantly attenuated expression in liver tissue of transgenic miR-100 mice that underwent a HFD for 16 weeks." (PMID 34488621, 2021). "Furthermore, obesity leads to release of pro-inflammatory mediators such as IL-1β, IL-6 and MCP-1, and then causes circulating monocytes recruitment and macrophages accumulation in adipose tissue." (PMID 35185543, 2021). "In this work, we assessed the presence of IL-1β within the muscle fibers; however, future studies will allow us to elucidate whether the skeletal muscle releases IL-1β during IR-associated obesity." (PMID 34638553, 2021). "Considering that obesity constitutes a major risk factor for the worst prognosis of breast cancer, the reduction of IL-1β in these patients induced by pesticides could constitute an additional aggravating factor." (PMID 32984049, 2020). "Additionally, we observed that blocking IL-1β activation pathways protects against HFD-induced obesity and associated liver steatosis in mice." (PMID 32002713, 2020). "Our results of increased frontal cortex levels of IL6 and IL1β and their strong association with an altered species diversity show that obesity-induced unique microbiome signature might exacerbate the proinflammatory microenvironment in the brain." (PMID 32927823, 2020). "In summary, we demonstrated that the presence of the 6 g spice blend in a HFCM significantly reduced postprandial IL-1β, IL-6, and IL-8 secretion from LPS-stimulated PBMCs in men with overweight/obesity at risk of CVD, suggesting a potential anti-inflammatory effect of spices." (PMID 32211803, 2020).
Obesity (continued). "In line with this view, our previous study highlighted the contribution of enteric glia in the onset of colonic motor alterations associated with HFD-induced obesity, through an increase in tachykininergic activity and release of pro-inflammatory mediators (i.e., IL-1β)." (PMID 32443525, 2020). "Furthermore, mice with myeloid HIF-1α deficiency showed lower levels of IL-1β expression in both WAT and the circulation than WT mice, consistent with HIF-1α being a key mechanism underlying IL-1β expression in the setting of obesity." (PMID 32221369, 2020). "The pro-inflammatory cytokine IL-1β has been implicated in the development of obesity and T2D." (PMID 33178196, 2020). "In obesity, adipokines are dysregulated, whereby inflammatory cytokines such as TNF-α, IL-6, IFN-γ, and IL-1β are upregulated, resulting in a state of chronic low-grade inflammation called metabolic inflammation which underlies pathophysiology of obesity and metabolic syndrome." (PMID 32403230, 2020). "An explanation for this association could be the fact that obesity might be considered as additional inflammation where pro-inflammatory adipokines, such as TNFα, IL1β, IL6 or MCP1, are segregated by adipose tissue and macrophages." (PMID 30786913, 2019). "Other extra-hepatic cell types such as adipocytes could also be important sources of IL-1α and IL-1β during NAFLD associated with obesity." (PMID 31507607, 2019). "Obesity was significantly associated with a higher increase in viral RNA quantities; a higher level of IL-8 at 24 h and a lower level at 72 h p.i.; and less pronounced increases in IL-1β and IP-10." (PMID 29581859, 2018). "Given that placental Ras expression and activity was increased with maternal obesity, we stimulated primary human trophoblast cells with bacterial endotoxin LPS or with proinflammatory cytokines IL-1β or TNF-α in order to mimic the inflammatory environment that is associated with obesity." (PMID 30402038, 2018). "Hence, HFD induced AHR in mice prior to the development of significant obesity which was associated with up-regulation of pulmonary IL-1β." (PMID 29686414, 2018). "Obesity is also associated with elevated levels of proinflammatory cytokines in the circulation and in tissues, and thus, we found that IL-1β, IL-4, and TNF-α levels in the serum were increased in the HFD group, and all of the three supplements sufficiently reduced these levels." (PMID 29023387, 2017). "In addition, hepatic stellate cells were reported to exhibit senescence-associated secretory phenotype in mice with obesity, secreting various inflammatory and tumor-promoting factors in the liver, including IL-1β, IL-6 and CXCL1." (PMID 28458256, 2017). "As these data suggest that NLRC4 inflammasome/IL-1β drives obesity-associated tumour angiogenesis through a signalling network between macrophages and adipocytes, we stained tumour sections for adipocytes and found a general increase in lipid droplets of tumours from DIO mice compared with ND mice." (PMID 27708283, 2016). "As inflammatory cytokines, including tumor necrosis factor alpha (TNFα) and interleukin 1 beta (IL1β), were reported to increase AM production, low-grade inflammation in fat tissues associated with obesity is assumed to be involved in the increased expression of AM." (PMID 25573159, 2015). "Low-grade inflammation in adipose tissues associated with obesity seems involved in the mechanism of the increased plasma AM level in obese subjects, because the AM production is up-regulated by inflammatory cytokines such as TNFα or IL1β." (PMID 25573159, 2015). "Saturated fatty acids from obesity-induced lipolysis are capable of activating macrophages and thereby activating NF-κB signaling, which in turn leads to transcriptional activation of genes encoding pro-inflammatory factors including IL-1β and IL-6." (PMID 25515685, 2014).